RANBP6 (RAN binding protein 6)
Description:
May function in nuclear protein import as nuclear transport receptor.
Tractability: PROTAC: ubiquitination databases record sites on it; its protein half-life has been measured.
Gene: Protein-coding gene on chromosome 9 (6,011,025 to 6,015,625, reverse strand). Ensembl gene ENSG00000137040.
Subcellular location: Cytoplasm; Nucleus
Subcellular location (Human Protein Atlas): Vesicles
Gene Ontology:
Molecular function: protein binding; nuclear import signal receptor activity
Biological process: protein import into nucleus
Cellular component: mitochondrion; cytoplasm; nucleus; synapse
Genetic constraint (gnomAD): Loss-of-function variants: 10 observed, 36.48 expected, observed/expected ratio (o/e) 0.27, 90% interval 0.17 to 0.47. The upper end of that interval is the gene's LOEUF score, 0.47, which puts it in group 2 of 6, group 1 being the genes least tolerant of losing a copy. Missense variants: 1,392 observed, 1,362.3 expected, observed/expected ratio (o/e) 1.02, 90% interval 0.98 to 1.07. Synonymous variants: 514 observed, 485.38 expected, observed/expected ratio (o/e) 1.06, 90% interval 0.98 to 1.14.
Homologues: Orthologues: pig RANBP6 (97% identical), guinea pig RANBP6 (96% identical), mouse Ranbp6 (96% identical), rat Ranbp6 (95% identical), Drosophila melanogaster Karybeta3 (49% identical), Caenorhabditis elegans imb-3 (33% identical), chimpanzee RANBP6 (33% identical), Caenorhabditis elegans imb-2 (13% identical). Paralogues in human: IPO5 (79% identical), IPO4 (20% identical), TNPO1 (15% identical), TNPO2 (15% identical), KPNB1 (12% identical).
Diseases named in the same sentence as RANBP6 in open-access papers:
RANBP6 is named in the same sentence as 7 diseases in open-access papers, as found by Europe PMC text mining. Sharing a sentence is not in itself a finding about the gene and the disease. The quoted sentences say what the papers report.
asthma (2 papers, 2019 to 2022). "Three known asthma loci replicated in CAAPA, after a Bonferroni correction for 810 association tests: chromosomes 9p24 (RANBP6, IL33), 15q22 (RORA,NARG2,VPS13C), and 17q12–q21." (PMID 30787307, 2019).
glioma (2 papers, 2017 to 2024). A benign or malignant brain and spinal cord tumor that arises from glial cells (astrocytes, oligodendrocytes, ependymal cells). "Lastly, we examined the effect of RanBP6 silencing on in vivo glioma growth using the RCAS-tva mouse glioma model." (PMID 29229958, 2017). "Focal and broad deletions including the RANBP6 gene locus were identified in glioblastoma (GBM) and RanBP6 silencing accelerated glioma growth in vivo." (PMID 29229958, 2017). "RanBP6 knockdown decreased survival, with mice injected with the RanBP6 shRNA living an average of 189 days (n = 10) and control mice living 275.5 days (n = 14) (p = 0.047, log-rank test) and promoted the development of higher-grade gliomas." (PMID 29229958, 2017). "Focal deletions of the RanBP6 locus on chromosome 9p were found in a subset of glioblastoma (GBM) and silencing of RanBP6 promoted glioma growth in vivo." (PMID 29229958, 2017).
glioblastoma (1 paper, 2017). The most malignant astrocytic tumor (WHO grade IV). "Here the authors show that the importin RanBP6 acts as a tumor suppressor in Glioblastoma and regulates EGFR signalling through promoting translocation of STAT3 to the nuclei and repressing EGFR transcription." (PMID 29229958, 2017).
tumor (2 papers, 2017 to 2020). "The variants in EXOG, RANBP2, RANBP6 and TNFRSF1B were sequenced in the tumour DNA of P1 to assess which allele of the gene was lost." (PMID 32357859, 2020). "Missense variants in four genes, EXOG, RANBP2, RANBP6 and TNFRSF1B, were identified in areas of LOH seen in the tumour from P1." (PMID 32357859, 2020). "Western blotting of five patient-derived GBM tumor spheres showed markedly decreased RanBP6 protein levels in one of the five tumor sphere lines (TS516 cells)." (PMID 29229958, 2017). "The missense variants in EXOG, RANBP6 and TNFRSF1B remained heterozygous in the primary tumour of P1, although with the loss of the second allele at a later stage, this does not necessarily exclude these variants as possible PMP predisposition genes on these data alone." (PMID 32357859, 2020). "Our data suggest that RanBP6 possesses similar tumor suppressor-like activity, at least in GBM." (PMID 29229958, 2017). "We therefore examined whether RanBP6 exhibits tumor suppressor-like activity." (PMID 29229958, 2017). "In human GBM tumor sections, we observed an inverse correlation between RanBP6 and EGFR protein levels and RanBP6 knockdown upregulated EGFR expression in the human GBM cell line LN18, consistent with earlier results in HEK-293T cells and MEFs." (PMID 29229958, 2017). "Four genes (EXOG, RANBP2, RANBP6 and TNFRSF1B) harboured missense variants that fell in a region of LOH in the tumour from the father only, but none showed somatic loss of the wild type allele in the tumour." (PMID 32357859, 2020). "RANBP6 was lower in tumor tissue compared to non-tumoral brain tissue." (PMID 29229958, 2017).
cancer (1 paper, 2017). A tumor composed of atypical neoplastic, often pleomorphic cells that invade other tissues. "Taken together, these findings suggest that RanBP6 serves as EGFR regulator that is disrupted in human cancer." (PMID 29229958, 2017).
RANBP6 also shares sentences with these, for which no sentence is quoted: breast carcinoma (1 paper); influenza infection (1).